EGF (epidermal growth factor)
Diseases named in the same sentence as EGF in open-access papers (continued):
Sharing a sentence is not in itself a finding about the gene and the disease.
Stroke (25 papers, 2014 to 2024). Sudden impairment of blood flow to a part of the brain due to occlusion or rupture of an artery to the brain. "CADASIL (cerebral autosomal dominant arteriopathy with subcortical infarcts and leukoencephalopathy) is the most common familial form of stroke, which is caused by mutations located in the epidermal growth factor (EGF)-like repeats of the NOTCH3 gene." (PMID 35223989, 2022). "The moderate to strong effect size of EGF+GHRP6 in the reduction of both stroke severity and resulting disability in treated patients provides additional evidence in favor of this therapeutic approach." (PMID 38638315, 2024). "The EGF+GHRP6 combined therapy for stroke was designed to activate a cascade of endogenous neuroprotection mechanisms, including regeneration of adult neural stem cells and repair in the penumbra zone." (PMID 38638315, 2024). "Although not powered for efficacy, this study revealed a significantly better outcome for EGF+GHRP6-treated patients relative to the clinical endpoints of stroke." (PMID 38638315, 2024). "In this study, the mean differences of NIHSS, Barthel index, and mRS exceeded their respective MCID in the subacute and chronic post-stroke phases, showing enhanced outcomes in those patients receiving EGF+GHRP6 therapy." (PMID 38638315, 2024). "In the present study we found that EGF levels in plasma from the stroke patients were nearly 6-fold lower than the levels in the age and gender matched control group." (PMID 35756121, 2022). "Some individuals (stroke: n = 6; control: n = 2) were identified as statistical outliers and had EGF levels several folds higher than the mean levels in the respective groups." (PMID 35756121, 2022). "As described, the evidence for neuroprotective effects of EGF in stroke derives from animals and cell cultures, and the translational value to human patients needs to be determined." (PMID 35756121, 2022). "This likely contributes to a reduced capacity for plasticity and tissue regeneration, suggesting that therapies to increase EGF levels during the acute phase of stroke would be beneficial." (PMID 35756121, 2022). "The effect of giving basic fibroblast growth factor (bFGF), fibroblast growth factor 2 (FGF-2) and epidermal growth factor (EGF) after stroke is uncertain." (PMID 35756121, 2022). "The level of EGF was almost 6-fold lower in the stroke patients (184 ± 403 pg/mL (mean ± SD) than in the healthy controls (1080 ± 599 pg/mL; p < 0.0001; Mann-Whitney U test; GraphPad Prism)." (PMID 35756121, 2022). "In a rat model of stroke, however, intraventricular infusions of EGF and erythropoietin (EPO) together promoted regeneration of the injured neocortex and reversed motor function deficits." (PMID 35756121, 2022). "PEG-EGF was able to penetrate deeper into the brain than the unmodified EGF, showing at least 2- and 7-fold greater protein accumulation in uninjured and stroke-injured brains, respectively." (PMID 33096803, 2020). "Here, we also found that levels of IL-1β, IL-1RA, IL-10, IL-13, IL-15, Flt-3L, Fractalkine, EGF, G-CSF and GM-CSF were lower in the severe stroke group." (PMID 31164999, 2019). "Infusion of a variety of neurotrophic growth factors, including basic fibroblast growth factor, epidermal growth factor and brain-derived neurotrophic factor, into the lateral ventricle of the rodent with stroke increases neurogenesis." (PMID 25867181, 2015). "The lower levels of BDNF and EGF found in the stroke patients compared to the healthy controls cannot with certainty be ascribed to stroke per se; the stroke patients could in theory have lower levels of these growth factors independently of the stroke." (PMID 35756121, 2022). "In stroke patients, plasma EGF varied between 16.5 and 2428 pg/mL, a 15-fold difference." (PMID 35756121, 2022). "Furthermore, the EGF levels were unaffected by the stroke size (p = 0.67; Kruskal-Wallis test; GraphPad Prism; data not shown)." (PMID 35756121, 2022).
Stroke (continued). "We therefore cannot conclude whether such a correlation exists, or if the difference in EGF levels between stroke patients and healthy controls would have been even larger if patients with more severe strokes had been included." (PMID 35756121, 2022). "In order to conclude whether EGF represent a therapeutic target in stroke, the data from the current study need to be confirmed in additional studies, perhaps also including persons with more severe strokes." (PMID 35756121, 2022). "A longer half-life (3.85 h) than EGF alone (1.69 h) was reported in stroke-injured brains." (PMID 33096803, 2020). "In this perspective, treatment of stroke conditions with growth factors, such as epidermal growth factor (EGF) and fibroblast growth factor (FGF) promoted the recruitment of endogenous NPCs and regenerated hippocampal circuitry, restoring synaptic function after ischemia." (PMID 32265815, 2020). "This suggests local and systemic cytoprotection induced by EGF+GHRP6 that eventually preserves organs and systems vulnerable to dysautonomies typical of stroke." (PMID 38638315, 2024). "The plasma level of CCL5 is highly correlated with BDNF, EGF (epidermal growth factor), and VEGF (vascular endothelial growth factor) after stroke; those trophic factors contribute to neuron growth and proper brain function." (PMID 39285280, 2024). "For EGF, there was an effect of stroke, an effect of OVX, and an interaction effect between stroke and OVX, with a significant increase in EGF expression after stroke in the RS OVX group." (PMID 37408003, 2023). "The intention to perform these histological investigations mainly resulted from our earlier report, which described a long-lasting reduction of the ischemic lesion volume after single and early treatment of experimental stroke with PEDF and EGF." (PMID 28445478, 2017). "In the studies with animal models of stroke, an increase in the expression of BDNF, GDNF, HGF, EGF, FGF-2, and IGF-1, as rapidly as 12 h after the insult and lasting until 5 days after stroke, has been described." (PMID 26607630, 2016). "We did not detect age or sex dependent changes in EGF levels in the present study, and EGF levels did not depend on the stroke size." (PMID 35756121, 2022). "With xenotransplantation of human MSCs in focal cerebral ischemia induced by artery occlusion in rat model, MSCs lead to improve function, reduce stroke volume and nerve protection granted to producing IGF-1, VEGF, epidermal growth factor (EGF) and bFGF (basic Fibroblast Groth Factor) in host brain." (PMID 28286618, 2017). "At 2 weeks after stroke, insignificant differences in the expression of reelin and EGF mRNA between the PBS, sham, and cell groups could indicate that reelin-mediated migration of progenitors and EGF-mediated recovery after stroke is time dependent." (PMID 24690461, 2014). "In both cases (EGF and EPO infusion and CsA infusion), functional recovery was observed in the stroke-injured animals, suggesting that new neurons are not necessary for the behavioral recovery." (PMID 25056698, 2014).
depression (24 papers, 2009 to 2026). "Our findings regarding the association of EGF with MDD would help to use EGF as a risk indicator of depression." (PMID 37399205, 2023). "On the other hand, the association of EGF levels with depression was shown a very few studies." (PMID 37399205, 2023). "Moreover, to the best of our knowledge, this investigation is the first attempt in Bangladesh to find out the involvement of serum leptin and EGF levels with depression and to find out their association with the severity of depression." (PMID 37399205, 2023). "Additionally, EGF has been associated with cellular proliferation and plasticity, however, its dysregulation, may contribute differently at various stages of depression." (PMID 41550142, 2026). "Altered levels of EGF and disruptions in its signaling pathways have been observed in depressive disorders, suggesting its role in the pathophysiology of MDD." (PMID 39385284, 2024). "In this investigation, it was shown that there was a relationship between serum EGF levels and major depression." (PMID 37399205, 2023). "We suggest further clinical investigations to determine the precise function of leptin and EGF in depression." (PMID 37399205, 2023). "Measuring the serum leptin and EGF levels alone cannot accurately represent the entire neuroinflammatory process of major depressive disorder." (PMID 37399205, 2023). "Serum IGF-1 levels were significantly negatively correlated with anxiety, depression, and cognitive dysfunction; serum EGF levels were significantly negatively correlated with cognitive dysfunction." (PMID 36383265, 2023). "It involves with depression in a different manner compared to EGF, as it acts as a neurotrophic factor." (PMID 37399205, 2023). "Thus, after considering this study’s findings as a possible candidate for depression and a risk indicator of MDD, we would like to suggest EGF." (PMID 37399205, 2023). "Our study findings suggest that reduced serum EGF levels have an impact on the pathogenesis of depression." (PMID 37399205, 2023). "The results of the present study show that EGF plays a very important role in the treatment of depression." (PMID 34479552, 2021). "Protein-protein interaction and KEGG enrichment analysis results show that prolactin signaling pathway and EGF play an important role in the treatment of depression." (PMID 34479552, 2021). "Luteoklin, quercetin, kaempferol and other active compounds in Epicedium can regulate multiple signaling pathways and targets such as IL6, AKT1, and EGF, therefore playing therapeutic roles in depression." (PMID 34479552, 2021). "This research indicated that prolactin signaling pathway and EGF play an important role in the treatment of depression." (PMID 34479552, 2021). "According to the results of this study, we can carry out research on prolactin signaling pathway and EGF in the future depression research." (PMID 34479552, 2021). "EGF can be used as another target for the treatment of depression, thus providing a new reference and ideas for the treatment of depression." (PMID 34479552, 2021). "These pathways are linked to the core genes chiefly including FOS, IL6, TNF-α, Bcl-2, c-Jun, ERK, and EGF gene in our research in the treatment of depression." (PMID 32997725, 2020). "As far as we know, there is scarce knowledge about the possible relationship between EGF, stress and depression." (PMID 27145079, 2016). "Plasma levels (pg/ml) of MCP-1, VEGF and EGF in relation to Exhaustion disorder (ED) diagnosis, degree of burnout, anxiety and depression in female patients and healthy controls." (PMID 19888340, 2009). "Reduced levels of EGF have been implicated in depression, but EGF levels were not predictive of depression severity." (PMID 39595087, 2024). "In addition, if any variation would be discovered, we sought to look into the relationship between changed serum leptin and EGF levels and the severity of depression." (PMID 37399205, 2023).
depression (continued). "Additionally, an intervention study found EGF may be a potential biomarker for anxiety and depression, given that cognitive behavioral therapy and mindfulness were found to significantly decrease EGF levels." (PMID 36960908, 2023). "However, limited studies have been conducted about EGF in depression." (PMID 34479552, 2021). "In this study, we investigated the involvement of EGF (a neurotrophic factor) and leptin (a pro-inflammatory cytokine) with MDD and depression severity." (PMID 37399205, 2023). "There is scarce knowledge on the possible relationship of EGF and MCP-1 in chronic stress and depression." (PMID 27145079, 2016). "Elevated serum IGF-1 levels in PD patients have been negatively correlated with nonmotor symptoms, such as anxiety, depression, and cognitive dysfunction, and combining IGF-1 with EGF enhances the diagnostic value for PD." (PMID 38699559, 2024). "This study shows that serum IGF-1 levels were correlated with the nonmotor symptoms of anxiety, depression, and cognitive dysfunction and that EGF levels were correlated with cognitive dysfunction." (PMID 36383265, 2023). "But the Pearson correlation study showed that the serum EGF levels and the severity of depression were not inversely proportional (r = -0.064, p = 0.364)." (PMID 37399205, 2023). "The key targets of Epicedium for treating depression were IL6, VEGFA, AKT1, and EGF." (PMID 34479552, 2021). "Furthermore, from sex-specific scatter plot graph where the distribution of serum EGF levels (pg/ml) against HAM-D score was depicted, it could be observed that the EGF levels were decreased in females more with the depression severity compared to males." (PMID 37399205, 2023). "But as per our investigation, the severity of depression is not correlated with altered EGF levels." (PMID 37399205, 2023). "MCP-1, EGF and VEGF levels were further investigated in relation to the measures of self-reported depression, anxiety and burnout irrespective of the ED diagnose." (PMID 19888340, 2009).
osteosarcoma (24 papers, 2010 to 2025). A usually aggressive malignant bone-forming mesenchymal neoplasm, predominantly affecting adolescents and young adults. "Other growth factors and cytokines, including epidermal growth factor (EGF) and interleukin-6 (IL-6), have also been implicated in promoting EMT in osteosarcoma, contributing to enhanced tumor invasion." (PMID 40075892, 2025). "Further investigation revealed elevated expression of key signaling molecules and pathways, such as epidermal growth factor (EGF) and interleukin-6 (IL-6), in recurrent osteosarcomas compared to their primary counterparts." (PMID 39534688, 2024). "The epidermal growth factor (EGF) also promotes MG63 osteosarcoma cell migration and invasion, as well as stress fibre formation via RhoA activation." (PMID 36899941, 2023). "Of the 13 osteosarcoma articles using induction and sphere-forming media, all utilized serum-free medium supplemented with factors, with EGF (epidermal growth factor) and FGF (fibroblast growth factor) being the most important, although in varying proportions." (PMID 37173919, 2023). "In osteosarcoma, EGF activates the MAPK/ERK and PI3K/Akt pathways, thus leading to cytoskeleton reorganisation, which in turn causes cell proliferation and migration." (PMID 34955078, 2022). "Functionality of EGFR in osteosarcoma cells was proven by EGF-mediated activation of both MAPK and PI3K/AKT pathway (determined by phosphorylation of ERK1/2, AKT, S6, and GSK3β)." (PMID 26526352, 2015). "This indicates that NF-κB plays a key role in EMT of osteosarcoma metastasis induced by EGF." (PMID 40786506, 2025). "In rat osteosarcoma cells, EGF induces the expression of Egr-1 mRNA, thus increasing mitogenesis." (PMID 34955078, 2022). "Furthermore, EGF has been found to be overexpressed in many types of cancers, including osteosarcoma." (PMID 36234645, 2022). "In our study we could demonstrate functionality of the EGFR in osteosarcoma cell lines leading to EGF-mediated activation of the MAPK and PI3K/AKT pathways." (PMID 26526352, 2015). "Thus, EGF-targeting agents should be evaluated to prevent osteosarcoma from deteriorating." (PMID 32665038, 2020). "Osteosarcoma cells express markedly distinct levels of functional EGFR, which is well-recognized by EGF-mediated downstream cascade activation of Ras, Raf, MEK, and Erk." (PMID 36765716, 2023). "EGF stimulation of the MAPK/ERK and PI3K/Akt pathways in osteosarcoma results in cytoskeleton rearrangement, promoting cell proliferation and migration." (PMID 36234645, 2022). "Epidermal growth factor (EGF) promotes cell epithelial-mesenchymal transition, metastasis, and progression of osteosarcoma by activating MAPK and PI3K/AKT pathway, which can be blocked by the EGFR-specific inhibitor gefitinib." (PMID 32665038, 2020). "When grown in serum-free semi-solid N2 medium with epidermal growth factor (EGF) and fibroblast growth factor basic (FGFb) in low attachment plates, MG-63 human osteosarcoma cells and primary osteosarcoma cells formed spheres at a frequency of 0.1 to 1%." (PMID 20979639, 2010). "Interestingly exogenous EGF upregulated viability of osteosarcoma cells in the majority but not all cell lines tested." (PMID 26526352, 2015). "In our study, TSP1 expression was stimulated in osteosarcoma cell lines by TGF-β1, not by other growth factors (VEGF, EGF, FGF-2), and this is accordance with previous study that TGF-β1 not EGF could stimulate TSP1 expression in osteosarcoma cell line MG63." (PMID 29100277, 2017).
thyroid cancer (24 papers, 2007 to 2025). "Second, SS inhibits EGF, a promoter of TC that is significantly positively associated with the risk of thyroid carcinoma (p(HR) = 0.03)." (PMID 39928612, 2025). "Survival analysis revealed that EGF is significantly positively associated with the risk of thyroid carcinoma (p(HR) = 0.03)." (PMID 39928612, 2025). "These growth factors include the insulin-like growth factor type 1, epidermal growth factor and the vascular endothelial growth factor, which could potentially increase the risk of thyroid cancer." (PMID 32517676, 2020). "Another growth factor, namely epidermal growth factor (EGF), is involved in promoting cell invasion and angiogenesis in thyroid carcinoma." (PMID 34204889, 2021). "TGF-α is an epidermal growth factor (EGF)-related protein, and is highly expressed in most kinds of thyroid carcinomas." (PMID 33046994, 2020). "We subsequently evaluated the rationale and efficacy of panitumumab in thyroid cancer and control cell lines after epidermal growth factor (EGF) stimulation and treatment with panitumumab using immunofluorescent Western blot analysis." (PMID 31443247, 2019). "Thyroid cancer cells also express EGF, TGF-α and its receptor, HER1, suggesting that they regulate thyroid cancer cell growth and invasion by autocrine and/or paracrine mechanisms." (PMID 23917679, 2013). "The low concentration of EGF in cancer patients observed in this study is in agreement with previous data concerning the serum of thyroid carcinoma." (PMID 20429940, 2010). "In addition, EGF/EGFR signal pathway plays a crucial role in the EMT progression of thyroid cancer cells." (PMID 34819077, 2021). "EGFR is activated by its ligand epidermal growth factor (EGF), which triggers a signal cascade, resulting in enhanced migration and invasion of thyroid cancer cells." (PMID 34819077, 2021). "In some thyroid cancers, epidermal growth factor (EGF) induces the proliferation, migration, and invasion of differentiated thyroid cancer cells, for instance, of FTC and PTC in vitro and in vivo." (PMID 30634497, 2019). "Previous studies have shown that EGF stimulates TIMP-1 expression in extravillous trophoblasts and thyroid carcinoma cells." (PMID 27509063, 2016). "Multiple receptor tyrosine kinases are overexpressed in thyroid cancer, including RET, rapidly accelerated fibrosarcoma (RAF) kinases, VEGF, mesenchymal epithelial transition factor, and epidermal growth factor." (PMID 26064704, 2015). "The addition of the shKLK7+EGF group further validated that KLK7 may function as an upstream regulator of EMT, facilitating thyroid cancer cell metastasis by promoting the MAPK/ERK signaling pathway and coordinating the EMT process." (PMID 39991575, 2025). "Moreover, RYR2 expression is correlated with poor prognosis in patients with thyroid carcinoma, and strong RYR2 upregulation was found in a BC cell line upon EGF-induced epithelial-to-mesenchymal transition." (PMID 34888385, 2021). "EGF and TGF-α have been demonstrated to be potent mitogenic factors for thyroid carcinoma cells." (PMID 23917679, 2013).